RN7SL97P (RNA, 7SL, cytoplasmic 97, pseudogene)
Gene: Miscellaneous RNA gene on chromosome 18 (25,818,234 to 25,818,532, reverse strand). Ensembl gene ENSG00000242216.
Homologues: Orthologues: chimpanzee Metazoa_SRP (98% identical), macaque Metazoa_SRP (93% identical). Paralogues in human: RN7SL1 (85% identical), RN7SL2 (85% identical), RN7SL3 (84% identical), RN7SL126P (82% identical), RN7SL147P (81% identical), RN7SL122P (80% identical), RN7SL296P (80% identical), RN7SL650P (80% identical), RN7SL543P (79% identical), RN7SL652P (79% identical), RN7SL679P (79% identical), RN7SL856P (79% identical), and 702 more.